BMI1 (BMI1 proto-oncogene, polycomb ring finger)
Diseases named in the same sentence as BMI1 in open-access papers (continued):
Sharing a sentence is not in itself a finding about the gene and the disease.
invasive carcinoma (2 papers, 2010 to 2013). A carcinoma that is not confined to the epithelium, and has spread to the surrounding stroma. "Our in vivo studies reveal a differential expression of Bmi1 in carcinoma in situ and invasive carcinomas compared to preneoplastic lesions." (PMID 23592995, 2013). "The increasing frequencies of Bmi-1 intensive expression in normal ovarian epithelium, to benign cystadenomas (3%), to borderline tumors (10%), and to invasive carcinomas were significant (37%, P < 0.05)." (PMID 20377880, 2010).
kidney cancer (2 papers, 2014 to 2023). Primary or metastatic malignant neoplasm involving the kidney. "Additionally, we treated MS147 to 786‐O cells, a kidney cancer cell line that contains a truncated, inactive VHL (and thus cannot be utilized by VHL‐recruiting PROTACs), to further demonstrate the correlation between MS147's BMI1/RING1B degradation activity and its antiproliferative effect." (PMID 36737841, 2023).
laryngeal squamous cell carcinoma (2 papers, 2012 to 2022). A squamous cell carcinoma that arises from the larynx. "Other human neoplasms, including colon, breast and Laryngeal squamous cell carcinoma show no amplification of Bmi1 although frequent protein over expression is observed in these tumors." (PMID 22574128, 2012).
lymphoid tumors (2 papers, 2012 to 2018). "Bmi1 is a proto-oncogene which was identified by its ability to initiate lymphoid tumors." (PMID 22574128, 2012).
male infertility (2 papers, 2022 to 2023). The inability of the male to effect fertilization of an ovum after a specified period of unprotected intercourse. "Based on our in vitro and in vivo data, we can conclude that we have demonstrated that BMI1 controls male infertility." (PMID 37139440, 2023). "Furthermore, Bmi1 knock-out mice exhibited impaired spermatogenesis, reduced serum testosterone levels, and male infertility." (PMID 35541907, 2022). "Altogether, our study not only reveals a novel mechanism for BMI1 in the process of SSC maintenance, but also provides a potential new strategy for treating male infertility." (PMID 35541907, 2022). "Our data strongly indicate that BMI1 is a crucial epigenetic mediator in SSC maintenance, and provide new targets for the treatment of male infertility." (PMID 35541907, 2022).
metastatic melanoma (2 papers, 2015 to 2022). A melanoma that has spread from its primary site to another anatomic site. "The BMI1 expression is higher in metastatic melanoma than in primary cancer, supporting the EMT-promoting activity of BMI1." (PMID 35455671, 2022).
muscular dystrophy (2 papers, 2018 to 2020). Muscular dystrophy (MD) refers to a group of more than 30 genetic diseases characterized by progressive weakness and degeneration of the skeletal muscles that control movement. "The senescence of myoblast has been associated with muscular dystrophy and with premature muscle wasting occurring in Bmi1 deficient young mice." (PMID 32572011, 2020). "Cellular senescence has been identified as a mechanism involved in the genesis of the myopathy associated with muscular dystrophy mouse model and related to premature muscle wasting in young mice deficient in the protein Bmi1 or mutant mice carrying BubR1 hypomorphic alleles." (PMID 30271655, 2018).
myeloid leukaemia (2 papers, 2012 to 2021). "SALL4 expression was strongly correlated with BMI-1 in most of the myeloid leukemia patient groups, providing a potential link between SALL4 and BMI-1 in leukemogenesis." (PMID 23067006, 2012). "Little is known about the expression pattern of the SALL4, ABCA3 and BMI-1 genes in patients with myeloid leukemia and patients that achieved complete remission after chemotherapy." (PMID 23067006, 2012). "Moreover, the phosphorylation of JNK is controlled by the cyclin CCNG2, which is a direct BMI1 target in myeloid leukaemia." (PMID 34316702, 2021). "Preliminary results indicate that BMI-1 may have potential as a therapeutic target for myeloid leukemia." (PMID 23067006, 2012). "The BMI-1 and SALL4 genes were detected in all of the PBMC samples from the healthy individuals and those with myeloid leukemia." (PMID 23067006, 2012). "In order to characterize the expression pattern of SALL4, BMI-1 and ABCA3 genes in patients with myeloid leukemia and those who achieved complete remission (CR) after chemotherapy." (PMID 23067006, 2012). "Further studies will be needed to determine whether BMI-1 and SALL4 are novel therapeutic targets for leukemic stem/initiation cells in primary myeloid leukemia." (PMID 23067006, 2012).
myeloid neoplasm (2 papers, 2015 to 2020). Proliferation of myeloid cells originating from a primitive stem cell. "There have been some reports on the Twist1/Bmi1-associated aggressiveness in myeloid neoplasms." (PMID 26832848, 2015). "It is important to point out that, in the context of myeloid neoplasms, the role of BMI-1 was associated with stemness control rather than cell proliferation." (PMID 33120864, 2020).
Myocardial fibrosis (2 papers, 2022 to 2025). "Metformin or rapamycin supplementation increased LVEF and LVFS, decreased HW/BW ratios and ameliorated hypertrophic features and myocardial fibrosis in WT and Bmi‐1–/– mice with Ang II treatment." (PMID 35390228, 2022). "In ischemia-induced myocardial fibrosis, BMI1 expression is upregulated." (PMID 40002810, 2025).
neural tumors (2 papers, 2012 to 2014). "Reported over expression of Bmi1 in astroglial and neural tumors." (PMID 22574128, 2012). "Both BMI1 and OCT-4 were shown to exert their functions in the other neural tumours by preventing cellular differentiation and contributing to their growth and progression." (PMID 25594028, 2014).
pulmonary fibrosis (2 papers, 2020 to 2023). Chronic progressive interstitial lung disorder characterized by the replacement of the lung tissue by connective tissue, leading to progressive dyspnea, respiratory failure, or right heart failure. "TGF-β1/IL-11/MEK/ERK signaling can mediate aging-related pulmonary fibrosis in a Bmi-1-deficient model of premature aging." (PMID 36845967, 2023). "We compared the effects of NAC treatment and p16 deletion on ameliorating aging-associated pulmonary fibrosis in Bmi-1-deficient mice." (PMID 31959867, 2020). "Therefore, we examined whether pulmonary fibrosis caused by Bmi-1 deficiency was associated with activation of TIME signals." (PMID 31959867, 2020). "Our results showed that NAC treatment significantly inhibited TGF-β1/IL-11/MEK/ERK signaling to prevent pulmonary fibrosis in Bmi-1−/− mice." (PMID 31959867, 2020).
renal carcinoma (2 papers, 2015 to 2017). A carcinoma arising from the epithelium of the renal parenchyma or the renal pelvis. "We also found a positive correlation between PVT1 and BMI1, ZEB1 and ZEB2 as well as a negative correlation between miR-200c and PVT1, BMI1, ZEB1 and ZEB2 in our 50 paired renal cancer tissues through RT-PCR, which was consistent with that of the analysis from TCGA Data Portal." (PMID 29156724, 2017).
retinal degeneration (2 papers, 2021 to 2025). Degeneration of the retina. "Our data demonstrate that AAV-mediated BMI1 gene delivery via either subretinal (AAV5) or suprachoroidal (AAV8) routes significantly protects against NaIO3-induced retinal degeneration." (PMID 40565365, 2025). "AAV8.BMI1-treated C57BL/6 mice also exhibited significant protection against NaIO3-induced retinal degeneration." (PMID 40565365, 2025). "In summary, this work established BMI1 gene therapy as a novel, mechanism-driven strategy to counteract chronic oxidative retinal degeneration." (PMID 40565365, 2025). "BMI1 was shown to play a major role during retinal degeneration and to better characterize its action, we deleted its expression specifically, either in the photoreceptors or the glial cells using a CRE recombinase approach." (PMID 34502238, 2021).
rhabdomyosarcoma (2 papers, 2009 to 2021). A rare aggressive malignant mesenchymal neoplasm arising from skeletal muscle. "Our analyses demonstrate that BMI1 is highly expressed in both fusion‐positive and fusion‐negative rhabdomyosarcoma." (PMID 33523558, 2021).
Salmonella Infections (2 papers, 2014 to 2017). Infections with bacteria of the genus SALMONELLA. "Moreover, Salmonella infection significantly decreased the expression of intestinal stem cell markers Lgr5 and Bmi1." (PMID 28588586, 2017). "Moreover, our western blot, PCR, and immunofluorescence data demonstrated that stem cell markers (Lgr5 and Bmi1) were significantly decreased by Salmonella infection (determined using GFP‐labeled Lgr5 organoids)." (PMID 25214524, 2014). "Moreover, we show that stem cell markers (Lgr5 and Bmi1) were decreased by Salmonella infection." (PMID 25214524, 2014).
skin aging (2 papers, 2022 to 2025). The gradual irreversible changes in structure of skin that occur as a result of the passage of time.. "We examined the changes in dermal morphology, proliferation, senescence, oxidative stress, and DNA damage to observe whether PQQ can prevent Bmi-1 deficiency-induced skin aging." (PMID 35187158, 2022). "It is uncertain whether Bmi-1 deficiency could lead to skin aging by redox imbalance and DNA damage." (PMID 35187158, 2022). "Based on the observations that oxidative stress in the skin is one of the core mechanisms mediating skin aging, we further determined whether skin aging phenotypes in Bmi-1−/− mice were associated with an alteration of redox balance." (PMID 35187158, 2022). "However, whether knockout of the Bmi-1 gene induces skin aging in mice and its underlying mechanisms remain to be further investigated." (PMID 40153371, 2025). "However, it is unclear whether PQQ can prevent Bmi-1 deficiency-induced skin aging by inhibiting oxidative stress and DNA damage." (PMID 35187158, 2022). "Our findings implied that Bmi-1 may be a novel target for delaying skin aging, which provides a theoretical and experimental basis for the clinical application of PQQ in the prevention and treatment of skin aging." (PMID 35187158, 2022).
thyroid (2 papers, 2021). "This study demonstrated a new biomarker for thyroid malignancies and found that the mRNA levels of the BMI-1 gene were higher in tumor tissues compared with healthy tissues." (PMID 34551814, 2021).
undifferentiated carcinoma (2 papers, 2010 to 2021). A usually aggressive malignant epithelial neoplasm composed of atypical cells which do not display evidence of glandular, squamous, or transitional cell differentiation. "In undifferentiated carcinomas, BMI-1 expression was heterogeneous, displaying a weak cytoplasmic staining." (PMID 34199929, 2021). "In stratified survival analysis, Bmi-1 expression could stratify the outcome of patients in hige-grade (grade 2/3) serous carcinoma (P = 0.045), mucinous carcinoma (P = 0.001) and undifferentiated carcinoma (P = 0.001) subgroups." (PMID 20377880, 2010).
uveal melanoma (2 papers, 2013 to 2022). A melanoma derived from melanocytes of the uveal tract. "We recently showed that HDAC inhibitors, which block BMI1, revert primary class 2 uveal melanoma cells to a differentiated class 1 phenotype." (PMID 23915344, 2013).
adenoid cystic carcinoma (1 paper, 2025). A malignant tumor arising from the epithelial cells. "In adenoid cystic carcinoma (ACC) Bmi-1 overexpression was correlated with high proliferative rate and unfavorable outcome." (PMID 39866230, 2025).
aging (1 paper, 2022). A developmental process that is a deterioration and loss of function over time. "The present study indicated for the first time that Bmi-1 and PQQ may play a key role in protection from skin aging." (PMID 35187158, 2022).
alopecia (1 paper, 2019). Hair loss usually from the scalp. "We have found that Bmi1+/− mice develop with age a neurological and progeroid syndrome characterized by alopecia, weight loss, abnormal paw clasping reflex and neuronal senescence." (PMID 30679733, 2019). "We observed that between the ages of 15–24 months (defined here as old mice), Bmi1+/− mice exhibited alopecia and reduced body size (~25%) when compared with age-match WT littermates." (PMID 30679733, 2019).
anaplastic oligodendroglioma (1 paper, 2016). A WHO grade III oligodendroglioma with focal or diffuse malignant morphologic features (prominent nuclear pleomorphism, mitoses, and increased cellularity). "The expression of Bmi-1 was reduced in the periphery of all subtypes except the Anaplastic Oligodendroglioma (AO), but without reaching significance." (PMID 27171431, 2016).
anaplastic thyroid cancer (1 paper, 2021). "Here we report that inhibition of the Shh pathway by Gli1 siRNA or by cyclopamine and GANT61 reduced BMI1 and SOX2 expression in SW1736 and KAT-18 cells, two anaplastic thyroid cancer cell lines." (PMID 33499351, 2021).
aspiration pneumonia (1 paper, 2021). "That is, the cause of death of Bmi-1-/- mice may be aspiration pneumonia caused by deterioration of oral hygiene in addition to deteriorated immune function due to hematopoietic defects." (PMID 33465144, 2021).
asthma (1 paper, 2025). "Additional miRNAs like hsa-miR-451a, miR-203a-3p, and miR-27a-5p were tied to asthma-related genes including MYC, EGFR, and BMI1, highlighting their involvement in airway inflammation and remodeling." (PMID 40806181, 2025).
bladder tumors (1 paper, 2009). "Intense expression of Bmi-1 protein was noted in 20.6%, 54.3%, and 78.8% of bladder tumors of histopathological grade G1, G2, and G3, respectively (P < 0.05, χ2 test)." (PMID 19228380, 2009).
brain glioma (1 paper, 2013). A malignant glioma that involves the brain. "Taken together, our data demonstrated that Bmi-1 induced tumor angiogenesis and VEGF-C expression in brain gliomas." (PMID 23383216, 2013).
breast adenocarcinoma (1 paper, 2009). "In this study, RNAi was introduced to down-regulate the expression of Bmi-1 in a highly malignant breast adenocarcinoma cell line, MCF-7." (PMID 21637439, 2009).
cervical adenocarcinoma (1 paper, 2016). An adenocarcinoma arising from the cervical epithelium. "Additionally, in human cervical adenocarcinoma cells BMI‐1 knockdown promotes the up‐regulation of HOXC13 expression, contributing to a block in cell proliferation." (PMID 27506447, 2016).
cervical squamous cell carcinoma (1 paper, 2021). A squamous cell carcinoma arising from the cervical epithelium. "It was found that the expression level of TAB2 was significantly positively correlated with that of BMI1 in cervical squamous cell carcinoma samples, which was also consistent with previous data." (PMID 34306095, 2021). "The StarBase database was used to analyze the coexpression of TAB2 and classical stemness molecules (BMI1 and SOX2) in 306 cervical squamous cell carcinoma samples." (PMID 34306095, 2021).
cholesteatoma (1 paper, 2023). A pathologic process characterized by the proliferation of keratinizing squamous epithelium resulting in the accumulation of keratin and cells in the middle ear and/or mastoid. "The authors demonstrated that miR-203a is downregulated in cholesteatoma keratinocytes and its target gene—Bmi1—is upregulated." (PMID 37047725, 2023). "Therefore, another signaling pathway model was proposed by the authors, suggesting that the miR-203a/Bmi1/p-Akt axis might participate in the development of cholesteatoma and become a future target in pharmacological treatment." (PMID 37047725, 2023).
chordoma (1 paper, 2023). Chordomas are rare malignant tumors arising from embryonic remnants of the notochord in axial skeleton. "Genes central for module 2 (and thus probably important for functioning of chordomas in both clusters) were either responsible for cell division and DNA repair process (e.g. ATM, CHEK, BMI1, MDM2) or parts of inhibitors of apoptosis cascade (e.g. CASP2, CASP8, SIRT2)." (PMID 37434245, 2023).
cognitive decline (1 paper, 2021). "BMI1 rs17415557 with the most significant association with CSF Aβ1-42 levels was also significantly associated with rates of cognitive decline, which was replicated in an independent cohort." (PMID 34610832, 2021). "In conclusion, the findings of our study from two independent well-characterized cohorts provide fundamental evidence that BMI1 and SNPs (rs17415557 and rs72814833) in BMI1 are associated with CSF Aβ1-42, a hallmark biomarker of AD, and cognitive decline rates." (PMID 34610832, 2021). "In view of recent pathophysiological evidence, we sought for the first time to investigate whether genetic variation in BMI1 is associated with a core AD biomarker and cognitive decline." (PMID 34610832, 2021). "BMI1 rs72814833, which is a 697 base pair upstream (5′) variant of BMI1 and highly correlated with rs17415557, is also significantly associated with CSF Aβ1-42 levels and rates of cognitive decline." (PMID 34610832, 2021).
colonic adenocarcinoma (1 paper, 2012). "From previous studies on gastric and colonic adenocarcinoma, Bmi-1 was found to upregulate both at the transcriptional and translational levels." (PMID 23078618, 2012).
cyst (1 paper, 2019). A sac-like closed membranous structure that may be empty or contain fluid or amorphous material. "Finally, we show that loss of Vangl2 lowers expression of the polycomb group repressor Bmi1 and hinders cyst formation, while overexpression of the gene rescues cyst formation in vitro." (PMID 31068622, 2019).
cystic fibrosis (1 paper, 2025). Autosomal recessive disorder caused by pathogenic variants in the CFTR gene (cystic fibrosis transmembrane conductance regulator), which encodes a chloride and bicarbonate channel expressed in epithelial cells, and follow the diagnosis criteria. "Ion channel activities were measured as short-circuit currents (Isc) of ENaC and CFTR in BMI1-transduced PCD airway epithelial cells and were compared to BMI1-transduced NHBE and cystic fibrosis cells (CFBE cells)." (PMID 41064994, 2025).
disc degeneration (1 paper, 2020). "In addition, we have demonstrated that the antioxidant NAC treatment can delay the disc degeneration caused by Bmi‐1 deficiency or IL‐1β and TNF‐α stimuli." (PMID 32583517, 2020). "This study investigated whether Bmi‐1 deficiency plays a role in promoting disc degeneration and the effect of treatment with antioxidant N‐acetylcysteine (NAC) on intervertebral disc degeneration." (PMID 32583517, 2020).
Duchenne muscular dystrophy (1 paper, 2017). Duchenne muscular dystrophy (DMD) is a neuromuscular disease characterized by rapidly progressive muscle weakness and wasting due to degeneration of skeletal, smooth and cardiac muscle. "The Polycomb group gene BMI1 is essential for efficient muscle regeneration in a mouse model of Duchenne muscular dystrophy, and its enhanced expression in adult skeletal muscle satellite cells ameliorates the muscle strength in this model." (PMID 28735850, 2017).
endometrial tumours (1 paper, 2008). "Also, the immunohistochemical expression pattern in endometrial tumours was concordant with the mRNA levels for BMI-1, indicating the relevance of BMI-1 protein in this tumour type." (PMID 18475299, 2008).
endometrioid carcinoma (1 paper, 2020). "Accordingly, the aim of the present study was to clarify the value of Bmi-1 as a marker of cell proliferation and its prognostic ability in endometrioid carcinoma." (PMID 32059385, 2020). "Materials and Methods: Bmi-1 expression was assessed in endometrioid carcinoma (grade 1–3) and normal endometrial tissues (in the proliferative and secretory phases) by immunohistochemistry; protein expression was evaluated using the nuclear labeling index (%) in the hot spot." (PMID 32059385, 2020). "Therefore, Bmi-1 may be a reliable proliferation and prognostic biomarker for endometrioid carcinoma." (PMID 32059385, 2020).